RNU6-786P (RNA, U6 small nuclear 786, pseudogene)
Gene: Small nuclear RNA gene on chromosome 6 (157,934,168 to 157,934,257, forward strand). Ensembl gene ENSG00000252658.
Homologues: Orthologues: chimpanzee U6 (96% identical), mouse Gm24765 (77% identical), pig U6 (77% identical), guinea pig U6 (74% identical), rabbit U6 (73% identical). Paralogues in human: RNU6-116P (80% identical), RNU6-20P (80% identical), RNU6-310P (80% identical), RNU6-411P (80% identical), RNU6-476P (80% identical), RNU6-1145P (79% identical), RNU6-1289P (79% identical), RNU6-1316P (79% identical), RNU6-188P (79% identical), RNU6-35P (79% identical), RNU6-38P (79% identical), RNU6-455P (79% identical), and 1287 more.